CRP (C-reactive protein)
Diseases named in the same sentence as CRP in open-access papers (continued):
Sharing a sentence is not in itself a finding about the gene and the disease.
AIDS (continued). "The inflammatory markers of concern are many but due to the biological and laboratory reproducibility of IL-6 and CRP, and their ability to predict the occurrence of non AIDS events, this study assessed the levels of CRP and IL-6 among PLHIV with dysglycemia in Tanzania." (PMID 31331321, 2019). "We observed a significant increase in CRP concentration in the HIV/AIDS septic patients." (PMID 23874739, 2013). "Similarly, heightened systemic inflammation, including elevated serum levels of C-reactive protein (CRP) and ferritin (an acute phase reactant), is associated with accelerated loss of lean body mass and a more rapid progression to AIDS and death." (PMID 21477359, 2011). "These associations persisted, and, in the case of sCD163 and CRP, increased in magnitude (aOR = 3.39, p = 0.01 and aOR = 2.26, p = 0.04, respectively), after additional adjustment for CD4, CD4 nadir, use of HAART, history of AIDS diagnosis, and 5-year HIV viral suppression." (PMID 30946765, 2019). "Our finding that AA was inversely associated with CRP and triglycerides and positively associated with HDL-C, CD4+ cell count and plasma albumin suggests that individual fatty acids may influence clinical outcomes in HIV/AIDS patients." (PMID 26161268, 2015). "Clinical trials further support CUR’s anti-inflammatory properties, showing reductions in markers such as C-reactive protein and TNF in people living with HIV/AIDS (PLWHA)." (PMID 40309788, 2025). "Notably, the majority of the associations between genetic susceptibility to AIDs and cancer were independent of the use of immunosuppressant drugs but partly mediated via peripheral red blood counts, platelet, white blood counts, and CRP." (PMID 40386413, 2025). "Serum levels of IL6, IL10, C-reactive protein (CRP), soluble (s)CD23, sCD27, and sCD30 are significantly higher in patients with HIV-NHL compared with HIV+ or AIDS controls after adjusting for numbers of CD4+ T-cells." (PMID 38482011, 2024). "For the logistic model for the need for mechanical ventilation, a significant effect was observed for the following variables: age, history of DM, history of HIV/AIDS, and admission labs including serum LDH and CRP." (PMID 32905551, 2020). "In the logistic model for the need for mechanical ventilation, a significant effect was observed for age, history of DM, history of HIV/AIDS, and serum LDH and CRP." (PMID 32905551, 2020). "In HIV+ men in the Multicenter AIDS Cohort Study (MACS), those with frailty had circulating CRP concentrations that were up to 50% higher than those in similar non-frail HIV+ men." (PMID 29097998, 2017). "CRP and LDH have been evaluated in the diagnosis of AIDS PCP and prediction of PCP severity but have been found to have low predictive value." (PMID 27579328, 2016). "Additional markers of innate immune activation, including interleukin-6 [IL-6] and the acute phase molecule C-reactive protein [CRP], are also predictive of non-AIDS HIV mortality." (PMID 26204934, 2015). "We suggest that the CRP can also be a useful biomarker of infection in HIV/AIDS septic patients similar to non-HIV septic patients." (PMID 23874739, 2013). "Therefore we calculated the Spearman correlation coefficients for plasmatic levels of IL-10, IL-22 and CRP and disease progression as defined by patients' viral load, CD4 cell counts, and AIDS-defining conditions." (PMID 20211031, 2010). "However, the level of lymphocyte, neutrophil, white blood cell, C-reactive protein, and procalcitonin in the group of patients without AIDS were significant higher than those of the AIDS group (P value < 0.05, one-way ANOVA)." (PMID 37430367, 2023). "Previous data have shown that non-AIDS comorbidities in PLWH are known to be influenced by metabolic, inflammatory, and viral factors; thus we tested markers related to such aspects, including GDF-15, suPAR, FGF-21, GLP-2, CRP, anti-CMV IgGs, and anti-EBV IgGs." (PMID 36093162, 2022).
AIDS (continued). "Although the levels of hs-CRP, ESR, and NLR were higher in patients with AIDs, the results were not obviously different between the two groups." (PMID 35390090, 2022). "Compared with the survivors, non-survivors with AIDS-PCP exhibited a lower albumin and higher D-dimer, CRP, LDH and Kyn/Trp ratio." (PMID 30832615, 2019). "Levels of CRP, WBC, LDH, HBDH, and Ferritin were significantly higher in the severe and nonsurvivor AIDS PCP patients." (PMID 27579328, 2016). "The IL-6, IL-10 and G-CSF levels were associated with hospital mortality in the HIV/AIDS septic group; however, the CRP levels and the surrogates of innate immune activation (cytokines) were similar among HIV/AIDS and non-HIV septic patients." (PMID 23874739, 2013). "We measured clinical parameters and biomarkers (C-reactive protein and cytokine levels) on the first day of septic shock and compared these parameters between HIV/AIDS and non-HIV patients." (PMID 23874739, 2013).
Allergy (51 papers, 2007 to 2026). An allergy is an immune response or reaction to substances that are usually not harmful. "Patients with SMPP exhibited significantly higher frequencies of allergic diseases, prolonged fever and steroid use, elevated inflammatory markers (CRP, LDH, D-dimer, ferritin, ALT), and higher PSQ and RQLQ scores (all p < 0.05)." (PMID 42074960, 2026). "The hypoxemia group exhibited a higher incidence of a history of allergic diseases and wheezing sounds, accompanied by substantial elevations in C-reactive protein levels and greater areas of CT involvement (P < 0.05)." (PMID 41166256, 2025). "Inpatients with preexisting allergies, decreased evaluated glomerular filtration rate, and increased high sensitivity C reactive protein or neutrophil-to-lymphocyte ratio prior to CAG had a higher probability of AU (odds ratio >1, P < 0.05 for all variables)." (PMID 34179031, 2021). "Third, high levels of CRP can occur in many acute conditions (such as infections and allergic reactions) and chronic conditions (such as cardiovascular disease)." (PMID 30768617, 2019). "The parameters for inflammatory diseases (CRP, TNFα and IL-6) and allergic diseases (IgE and eosinophil) were similarly unchanged, suggesting that ARA intake does not evoke inflammatory or allergic diseases." (PMID 22188761, 2011). "The presence or absence of hypoxemia was used as the dichotomous dependent variable, while the independent variables included a history of allergic diseases, positive aeroallergen test, positive food allergen test, wheezing sounds, CRP, D-dimer, and the number of infected lung lobes." (PMID 41166256, 2025). "Other biomarkers for AD severity include markers correlated with general inflammation or allergy such as C-reactive protein (CRP), serum lactate dehydrogenase (LDH), peripheral eosinophil count and serum eosinophil cationic protein (ECP), a protein released during the degranulation of eosinophils." (PMID 36012878, 2022). "Markers related to general inflammation or allergies such as C-reactive protein, serum lactate dehydrogenase, periostin, and peripheral eosinophil counts may be included as biomarkers correlated with clinical severity of AD." (PMID 36362483, 2022). "In 20 individuals who completed the survey (average age 46 years, 75% females), allergy to house dust was significantly associated with increased IPDI (adjusted for age) and significantly increased odds of potentially unhealthy values of total IgA, IL-1β, and CRP." (PMID 39910646, 2025). "His fever, elevations of the white blood cell count and CRP as well as the poor response of the skin rash to antihistamines and glucocorticoid ointment suggested an infection rather than an allergy or immunological disorder." (PMID 39801600, 2025). "CRP is also a commonly used indicator in the clinical diagnosis of pulmonary infection; however, non-infectious diseases, such as allergies and autoimmune disorders, can influence CRP levels." (PMID 39635594, 2024). "By contrast, the CRP values in the POx-PSA group were much lower than those of the PSA group, suggesting that no adverse event occurred because of an allergic reaction." (PMID 37316550, 2023).
dyslipidaemia (51 papers, 2008 to 2025). "The novelty of our study lies in the comparison of four markers of cardiovascular risk: dyslipidaemia [lp(a)], insulin reistance (leptin), inflammation (hs-CRP) and matrix remodelling (PAPP-A), as possible predictors of plaque instability." (PMID 22836155, 2012). "SUA levels are elevated in association with the severity of sudomotor dysfunction and they are associated with increased CRP and dyslipidaemia." (PMID 21941527, 2011). "In major depressed individuals with dyslipidaemia, body mass index, triglyceride levels, and CRP levels were higher than those in major depressed individuals without dyslipidaemia." (PMID 35755481, 2022). "In terms of inflammatory markers, those with dyslipidaemia were more likely to have higher CRP, LDH, procalcitonin, white cell count and neutrophil count but lower lymphocyte count." (PMID 33060704, 2020). "Confirming the recent data on the association between systemic inflammation and dyslipidaemia in OSA, lipid markers except for ApoA1 and LPA correlated with CRP." (PMID 30712133, 2019). "When patients with ACR ≤ 300 mg/g were compared with those with ACR >300 mg/g, the latter have higher percentage of grades II-IV retinopathy, higher levels of serum uric acid, C-reactive protein and dyslipidaemia than the former." (PMID 28828178, 2016). "studies used supplementation with DHA (docosahexaenoic acid) and EPA (eicosapentaenoic acid), precursors of anti-inflammatory eicosanoids previously shown to reduce CRP in subjects presenting with dyslipidaemia or higher baseline inflammatory status, as synthetized in Guo’s meta-analysis." (PMID 38476230, 2024). "It has been used in several studies, including used with comorbidity data to predict kidney replacement therapy within 12 months of CKD diagnosis, and creation of biomarker panels using kidney measurements, dyslipidaemia biomarkers, serum sodium, and c-reactive protein to determine progressive CKD." (PMID 33327377, 2020). "Furthermore, increased inflammation, such as via increased C-reactive protein (CRP) levels, may be related to the progression of dyslipidaemia-induced arterial stiffness." (PMID 38909224, 2024). "Attenuation of TAG, total cholesterol, LDL, VLDL, C-reactive protein with corresponding increase in HDL in the finasteride or test groups 1 and 2 rats suggest the capacity of finasteride or S. malaccense to ameliorate dyslipidaemia." (PMID 39086866, 2024).
giant cell arteritis (48 papers, 2008 to 2025). "A retrospective case series reported that in giant cell arteritis, baricitinib and tofacitinib reduced inflammatory markers (C-reactive protein and erythrocyte sedimentation rate) and corticosteroid use without relapses." (PMID 40948684, 2025). "In the case of a patient with giant cell arteritis, for example, saliva CRP was more accurate than urine CRP in predicting serum CRP levels." (PMID 40856619, 2025). "In the present case, the significant increase in both ESR and CRP further supported the suspicion of giant cell arteritis." (PMID 40225509, 2025). "These 2 patients had positive ultrasound findings for temporal arteritis and the highest CRP levels at presentation of the cohort." (PMID 36697134, 2023). "At this time, due to the elevated ESR and CRP, temporal arteritis was considered a lower differential that needed to be ruled out." (PMID 35919218, 2022). "In these cases, the arteritis was diagnosed based on bruits observed in physical examination, unexplained elevated CRP levels and aortitis as an incidental finding in an MR-enteroclysis, respectively." (PMID 34143786, 2021). "A very high value of CRP is a strong parameter for the diagnosis and the treatment of several diseases, such as cell giant arteritis (also called temporal arteritis or Horton's disease), vasculitis Takayasu disease and polymyalgia rheumatica." (PMID 23516433, 2013). "In arteritic AION, patients may have symptoms of giant cell arteritis, reduced temporal artery pulses, and elevated CRP, ESR and/or platelets." (PMID 38867071, 2024). "Inflammatory blood tests, complete blood count, erythrocyte sedimentation rate, and C-reactive protein were arranged to rule out giant cell arteritis (GCA) as a cause of the suspected NA-AION in the right eye." (PMID 39618581, 2024). "Classical inflammatory indices such as C-reactive protein (CRP) and erythrocyte sedimentation rate (ESR) are considered key markers of the disease to date but the diagnostic gold standard is still the temporal artery biopsy showing arteritis." (PMID 39633039, 2024). "Non-invasive superficial temporal artery ultrasound detecting inflammatory thickening of the intima as the “halo” sign combined with routine elevated erythrocyte sedimentation rate and C-reactive protein may be helpful in diagnosing patients with a high probability of having giant cell arteritis." (PMID 35795624, 2022). "A laboratory workup was conducted to exclude the presence of a new acute condition, most notably giant cell arteritis (GCA) (ESR, CRP, and platelet count)." (PMID 40979012, 2025). "Temporal arteritis was suspected, and inflammatory markers, including erythrocyte sedimentation rate (ESR) and C-reactive protein (CRP), were within normal limits." (PMID 41589175, 2025). "The differential diagnosis included giant cell arteritis (GCA) due to the visual changes and elevated ESR and CRP." (PMID 39886706, 2024). "During therapy with Tocilizumab, CRP can no longer be used reliably as an indication of disease activity or relapse of giant cell arteritis, which emphasizes the importance of the additional use of imaging techniques." (PMID 38020122, 2023). "Although not a specific marker for the diagnosis of giant cell arteritis, serum CRP is commonly used for disease monitoring during treatment." (PMID 38020122, 2023). "The patient had no clinical signs of giant cell arteritis (jaw claudication, headache, and scalp tenderness), and CRP and ESR were within the normal range." (PMID 34945256, 2021). "For example, rare, rheumatologic diseases (e.g., giant cell arteritis and polymyositis) may be simultaneously present, hence further investigations (e.g., ESR and CRP) may be required upon clinical suspicion." (PMID 30050433, 2018). "Little evidence exists to support laboratory tests such as serum ESR or CRP to rule out temporal arteritis." (PMID 27833680, 2016).
giant cell arteritis (continued). "In addition, a vasculitic cause (i.e. Giant Cell Arteritis) is also less plausible because of a normal ESR, CRP, no history consistent with temporal arteritis, and failure to progress despite the absence of corticosteroid treatment." (PMID 23926927, 2013). "We report a rare case of extensive CVST initially treated as giant cell arteritis (GCA) due to unilateral temporal headache, elevated CRP, and a negative D-dimer." (PMID 41211275, 2025). "We present a case of a 66-year-old male with a classic clinical presentation of temporal arteritis with a normal erythrocyte sedimentation rate (ESR), C-reactive protein (CRP), and negative bilateral temporal artery biopsies." (PMID 36475126, 2022). "There were no specific symptoms or signs suggestive of giant cell arteritis (GCA) but the erythrocyte sedimentation rate (ESR) was 98 mm/hour and the C-reactive protein was more than 139 mg/dl, which prompted the physicians to arrange a temporal artery biopsy." (PMID 18534004, 2008). "Vasculitides (giant cell arteritis, GPA) were unlikely with normal ESR/CRP and negative ANCA." (PMID 41415515, 2025). "None had clinical suspicion of giant cell arteritis, having all normal ESR and CRP values." (PMID 37735668, 2023).
interstitial lung disease (48 papers, 2015 to 2026). A diverse group of lung diseases that affect the lung parenchyma. "Prior studies have found that male gender, older age, and elevated levels of C-reactive protein (CRP) are risk factors associated with the development of interstitial lung disease in patients with primary Sjögren’s syndrome." (PMID 38721305, 2024). "High WBC, CRP, and IL-6 levels in patients with acute exacerbation of interstitial lung disease are known to be associated with the patient’s prognosis." (PMID 35566611, 2022). "Serum levels of ESR and CRP are risk factors of interstitial lung disease (ILD) in DM/PM, elevated ESR is associated with increased mortality in patients with DM, and CRP has positive correlation with the global activity scores in DM." (PMID 29976235, 2018). "In addition, other study reported that AE-IP occurred 6.3% of patients with interstitial lung disease, and only high preoperative C-reactive protein (CRP) level was identified a risk factor." (PMID 31307466, 2019). "The upregulation of CRP is associated with a poor prognosis in follicular lymphoma patients undergoing rituximab-containing chemotherapy and may indicate immunochemotherapy-related interstitial lung disease in B-cell lymphoma." (PMID 37500057, 2023). "Roseburia was negatively correlated with myoglobin (MYO), cardiac troponin T (cTnT), ESR, CRP, and the occurrence of interstitial lung disease (ILD)." (PMID 37692165, 2023). "Tocilizumab, an IL-6 inhibitor, has been FDA approved for the treatment of interstitial lung disease in SSc, especially effective in the inflammatory phase of disease (patients with high C-reactive protein)." (PMID 37372943, 2023). "Additionally, ethane is an additional biomarker of lipid peroxidation and has a direct correlation with the plasma lactate dehydrogenase level and C-reactive protein in patients with interstitial lung disease." (PMID 38318837, 2024). "In this study, we found that CRP was significantly elevated in patients with non-infectious diseases such as hypersensitivity pneumonia and connective tissue disease-associated interstitial lung disease." (PMID 39635594, 2024). "It is hypothesized that bronchoalveolar lavage (BAL) neutrophilia, Krebs von den Lungen-6 (KL-6), and C-reactive protein (CRP) predict the severity of chronic fibrosing interstitial lung diseases (CF-ILDs)." (PMID 37602059, 2023). "In the univariate analysis, age, male sex, BVAS, FFS, interstitial lung disease, serum creatinine levels, serum albumin levels, C‐reactive protein (CRP) levels, and underweight based on the new BMI category at diagnosis were associated with all‐cause mortality during the follow‐up." (PMID 35312104, 2022). "Higher mortality was significantly associated with lower BMI, lower Barthel Index, higher Hugh-Jones grade, higher A-DROP score, CRP ≥ 20 mg/dL or infiltration of least two-thirds of one lung, mechanical ventilation at admission, interstitial lung disease and aspiration pneumonia." (PMID 34732194, 2021). "We found that pediatric disease onset, severe limb weakness, dysphagia, muscle atrophy, absence of interstitial lung disease, and elevated C-reactive protein were associated with the poor outcome." (PMID 25963141, 2015). "SAVI typically presents with systemic inflammation, recurrent fever, interstitial lung disease (ILD), cutaneous vasculopathy, and systemic inflammation with elevated C-reactive protein (CRP) and type I IFN activation." (PMID 36275728, 2022). "Similarly, C-reactive protein (CRP) can serve as a biomarker to discriminate between inactive and active cases, and also distinguishing sarcoidosis from interstitial lung disease (ILD) and chronic hypersensitivity pneumonitis." (PMID 38250062, 2023). "Regarding the two excluded studies, one focused on patients with ASS with severe interstitial lung disease (ILD), who had poor basic health conditions and six patients had unexplained fever and increased CRP levels." (PMID 36578492, 2022).